ZNF142 (zinc finger protein 142)
Description:
May be involved in transcriptional regulation.
Synonyms: KIAA0236; pHZ-49; HA4654; NEDISHM
Tractability: PROTAC: UniProt records ubiquitination sites on it; ubiquitination databases record sites on it.
Gene: Protein-coding gene on chromosome 2 (218,633,329 to 218,659,655, reverse strand). Ensembl gene ENSG00000115568.
Subcellular location: Nucleus
Subcellular location (Human Protein Atlas): Nucleoli fibrillar center; Nucleoplasm
Gene Ontology:
Molecular function: DNA-binding transcription factor activity, RNA polymerase II-specific; RNA polymerase II transcription regulatory region sequence-specific DNA binding
Biological process: regulation of transcription by RNA polymerase II; regulation of gene expression
Cellular component: nucleus
Genetic constraint (gnomAD): Loss-of-function variants: 93 observed, 132.73 expected, observed/expected ratio (o/e) 0.7, 90% interval 0.59 to 0.83. The upper end of that interval is the gene's LOEUF score, 0.83, which puts it in group 3 of 6, group 1 being the genes least tolerant of losing a copy. Missense variants: 2,077 observed, 2,362.3 expected, observed/expected ratio (o/e) 0.88, 90% interval 0.85 to 0.91. Synonymous variants: 796 observed, 905.55 expected, observed/expected ratio (o/e) 0.88, 90% interval 0.83 to 0.93.
Homologues: Orthologues: macaque ZNF142 (96% identical), chimpanzee ZNF142 (89% identical), mouse Zfp142 (84% identical), rat Zfp142 (84% identical), tropical clawed frog znf142 (47% identical), zebrafish znf142 (36% identical). Paralogues in human: ZNF91 (10% identical), ZNF84 (10% identical), ZNF99 (9% identical), ZNF729 (9% identical), ZNF107 (9% identical), ZNF160 (9% identical), ZNF208 (9% identical), ZNF420 (9% identical), ZNF184 (8% identical), ZNF473 (8% identical), ZNF845 (8% identical), ZNF569 (8% identical), and 24 more.
Diseases named in the same sentence as ZNF142 in open-access papers:
ZNF142 is named in the same sentence as 8 diseases in open-access papers, as found by Europe PMC text mining. Sharing a sentence is not in itself a finding about the gene and the disease. The quoted sentences say what the papers report.
Intellectual disability (2 papers, 2021 to 2022). "Biallelic variants of the gene encoding for the zinc‐finger protein 142 (ZNF142) have recently been associated with intellectual disability (ID), speech impairment, seizures, and movement disorders in nine individuals from five families." (PMID 35616059, 2022).
neurodevelopmental disorder (3 papers, 2020 to 2024). A behavioral and cognitive disorder with onset during the developmental period that involves impaired or aberrant development of intellectual, motor, or social functions. "In addition, genetic variants within ZNF142, a gene coding for a zinc-finger protein, have been associated with a neurodevelopmental disorder resulting in speech impairment and intellectual disability." (PMID 32424139, 2020).
ZNF142 also shares sentences with these, for which no sentence is quoted: tumor (2 papers); Cognitive impairment (1); melanoma (1); movement disorder (1); pancreatic adenocarcinoma (1); pancreatic cancer (1).